GLDC (glycine decarboxylase)
Diseases named in the same sentence as GLDC in open-access papers (continued):
Sharing a sentence is not in itself a finding about the gene and the disease.
tumor (continued). "Therefore, we future examined whether GLDC was correlated with the tumor immune infiltration in TNBC." (PMID 36275705, 2022). "Therefore, repeating shAON treatment in our mouse model might result in the accumulation of GLDC-shAON in the body which in turn led to tumor suppression." (PMID 29911072, 2018). "The expression of GLDC which is unique to the CR population was shown to induce dramatic changes in glycolysis, glycine/serine and pyrimidine metabolism, regulate cancer cell proliferation and was shown to be essential for the sustenance of tumor initiating non-small cell lung cancer." (PMID 27470985, 2016). "Here we report that GLDC is polyubiquitinated at K636 following EGFR activation, which drives GLDC-dependent transcriptional inhibition of MHC-I genes and induces tumor cells to evade CD8+ T cell-mediated immunosurveillance." (PMID 41728086, 2026). "To further explore the role of GLDC in HCC, we performed immunohistochemistry staining using tissue microarray and detected GLDC protein expression in HCC and para-tumor tissue samples." (PMID 41550650, 2025). "Intriguingly, induced GLDC remarkably attenuated epithelial-mesenchymal transition (EMT) progress and tumor growth in vitro and in vivo." (PMID 41550650, 2025). "Glycine decarboxylase (GLDC) is the key limiting enzyme in glycine breakdown metabolism and acts as oncogene or tumor suppressor to impact tumor onset and progression in a context dependent manner." (PMID 41550650, 2025). "We then assessed the expressions of GLDC and ISGF3 in xenografted tumor tissues and confirmed decreased GLDC and increased IRF9 and STAT2 expressions." (PMID 39781465, 2025). "Herein, we found that increased ISGF3 induced by depletion of GLDC impairs proliferation of RCC cells, exacerbates CP-induced DNA damage, and decreases tumor growth in the mice." (PMID 39781465, 2025). "Thus, in agreement with reducing the GLDC+ and ALDH+ subpopulations, LDHB silencing reduced the synthesis of pyrimidine and retinoic acid, both of which are critically associated with maintaining a stem-like state linked with increased tumor initiation capacity." (PMID 35877003, 2022). "The enzyme glycine decarboxylase (GLDC), which belongs to the glycine cleavage system, is downregulated in HCC cells to support tumour progression and metastasis." (PMID 34588983, 2021). "Thus, targeting SUCLG1, PCK2, GLDC protein may be a useful strategy to inhibit tumor progression." (PMID 32699530, 2020). "Moreover, many genes have been found to control PCa tumor growth by regulating glycolysis, such as HOXA11-AS and GLDC." (PMID 40366506, 2025). "In contrast, we found that knockdown of GLDC, not overexpression of GLDC, inhibits cellular proliferation and tumor growth." (PMID 39781465, 2025). "Based on previous studies showing that mtDNA stress activates innate immune systems via unphosphorylated-ISGF3 (U-ISGF3) and that ISGF3 acts as a tumor suppressor in RCC 16, 18, 29, we hypothesized that GLDC could regulate RCC progression via ISGF3." (PMID 39781465, 2025). "GLDC acetylation at K514 enhances its interaction with VPS34, thereby tremendously inhibiting malignant features such as cell proliferation, migration, autophagy and tumor growth in HCC." (PMID 41550650, 2025). "However, PDGDH and GLDC are overexpressed in many human cancer cells, whilst CDO1 is a known tumour suppressor gene in many human cancer cells." (PMID 39595653, 2024). "In poorly vascularized tumor regions, cancer cells depend on serine and glycine metabolism for survival, highlighted by high levels of mitochondrial serine hydroxymethyltransferase (SHMT2) and glycine decarboxylase (GLDC)." (PMID 37298093, 2023). "By univariate Cox regression analyses, GLDC downregulation, TNM stage, BCLC stage, satellite metastasis, macrovascular invasion, microvascular invasion, tumor size, intraoperative blood transfusion, surgery time, and intraoperative hemorrhage were significantly correlated with worse OS." (PMID 30804330, 2019).
tumor (continued). "Thus, in this study, we used steric hindrance antisense oligonucleotide (shAON) to inhibit GLDC, followed by hyperpolarized 13C-pyruvate MRS to measure tumor metabolism." (PMID 29911072, 2018). "Expectedly, exon skipping was observed in the tumor tissues of GLDC group but not in the Veh and Scr groups." (PMID 29911072, 2018). "From The Cancer Genome Atlas (TCGA), we observed that GLDC is highly upregulated in several tumor types versus its respective non-cancerous samples." (PMID 29911072, 2018). "Even though increased GLDC gene expression was observed in mice administered with Dox water, tumor growth was not rescued." (PMID 27391339, 2016). "Here, we show that glycine decarboxylase (GLDC), a key enzyme in glycine metabolism, functions as an inhibitor of MHC-I expression in EGFR-activated tumor cells to induce immune escape by a mechanism independent of its enzymatic activity." (PMID 40926122, 2025). "Therefore we may argue that tumor cells with high SHMT2 level, such as Huh-7 cells, are sensitive to GLDC inhibition because excess glycine is not metabolized rapid enough via the glycine cleavage system, as evident from our results seen in the Huh-7 cells with GLDC knockdown." (PMID 27391339, 2016). "Given the finding that multiple tumor suppressors regulate a HIF-dependent negative feedback loop via ISGF3 18, GLDC could be a promising therapeutic target for the treatment of RCC." (PMID 39781465, 2025).
cancer (46 papers, 2014 to 2026). A tumor composed of atypical neoplastic, often pleomorphic cells that invade other tissues. "GCS is the primary enzymatic system for glycine catabolism in the human body, wherein GLDC, which encodes the glycine decarboxylase protein, has been found to be significantly upregulated in various cancers, including PCa." (PMID 39859489, 2025). "GLDC inhibition impairs pyruvate metabolism in cancer cells, resulting in loss of their metabolic energy source." (PMID 35873461, 2022). "Components of GCS, especially GLDC, are frequently overexpressed in different malignancies and this is linked with cancer progression." (PMID 28177894, 2017). "The role of GLDC in cancer development and progression has only recently been elucidated and appears complex and controversial." (PMID 39781465, 2025). "Among these, HOXB13 (involved in skin development) and GLDC (a component of the glycine cleavage system) are both known TSGs that are epigenetically silenced in many cancers and promote apoptosis and autophagy, respectively." (PMID 37245006, 2023). "GLDC inhibition impaired cancer cells survival with high SHMT2 levels due to an excess of glycine, not metabolized by GLDC, which is thus converted to toxic molecules (aminoacetone and methylglyoxal)." (PMID 37298093, 2023). "We also investigated the expression of GLDC mRNA in several organs (gTEX.org) and the expression of its protein (Protein Atlas) and mRNA (TCGA) in several cancer types." (PMID 37923835, 2023). "In contrast, the glycine decarboxylation system of cancer cells can break down glycine in the presence of the glycine decarboxylase complex to form ammonia, carbon dioxide, and methylenetetrahydrofolate." (PMID 38057864, 2023). "GLDC provokes significant alterations in glycolysis and glycine/serine metabolism, resulting in changes in pyrimidine metabolism and the regulation of cancer cell proliferation." (PMID 37242225, 2023). "For example, GLDC is essential for the formation of cancer-initiating cells in non-small cell lung cancer (NSCLC) (8." (PMID 37781511, 2023). "The secreted lactate fuels NSCLC TICs featuring cancer stem cell markers, e.g., increased GLDC expression, OXPHOS, and ALDH activity." (PMID 35877003, 2022). "In the present study, our results showed that GLDC, which was significantly up-regulated in cancer tissues, facilitated cell proliferation and was negatively correlated with the RFS and DMFS in TNBC." (PMID 36275705, 2022). "For example, glycine decarboxylase (GLDC) gene is often upregulated in lung, brain, prostate, and other cancers and provides a growth advantage to cancer cells by regulating glycine catabolism during nucleotide synthesis." (PMID 35189921, 2022). "In the present study, our results showed that GLDC, significantly upregulated in cancer tissues, was correlated with a worse prognosis related to RFS and DMFS in TNBC." (PMID 36275705, 2022). "Glycine decarboxylase (GLDC) is commonly upregulated in cancers, and the mTORC1 activity regulates the posttranslational modifications of GLDC, which contribute to the modulation of glycine metabolism and tumorigenesis." (PMID 36613455, 2022). "We suggest that GLDC inhibition leads to impairment in pyruvate metabolism thus possibly hindering cancer cells from acquiring critical metabolic fuels." (PMID 29911072, 2018). "Despite significant cytotoxicity was observed in scramble-shAON, GLDC-shAON is much more potent therefore producing wider therapeutic window especially when cancer cells express high level of GLDC." (PMID 29911072, 2018). "Taken together, our findings illustrate that pyruvate metabolism decreases upon GLDC inhibition, thereby starving cancer cells from critical metabolic fuels." (PMID 29911072, 2018). "Nonetheless, our results demonstrate that GLDC inhibition impairs pyruvate metabolism, thus starving cancer cells from metabolic fuels." (PMID 29911072, 2018).
cancer (continued). "SHMT1/2 and GLDC are important genes in the serine–glycine metabolic pathway that are reported to be upregulated in many cancers." (PMID 29911072, 2018). "Given the fact that cancer cells are characterized by a high demand for C1 bodies to ensure continuous growth, enzymes of glycine metabolism, such as GLDC, are overexpressed in tumorigenic tissue." (PMID 30337557, 2018). "Glycine decarboxylase (GLDC) gene is frequently upregulated in various types of cancer including lung, prostate and brain." (PMID 29911072, 2018). "GLDC was most frequently expressed in cancer cells and stroma of the HER-2-positive cancers and least frequently in TNBC (p<0.001)." (PMID 24979213, 2014). "Hence, the role of GLDC in cancer development and progression seemingly differs amongst different cancer types." (PMID 39781465, 2025). "Little is known regarding the function of GLDC in tumorigenesis; moreover, the function of GLDC in tumorigenesis may seemingly vary in a cancer-type dependent manner." (PMID 39781465, 2025). "GLDC was found to be involved in cancer growth through the PSAT1/Serine/SHMT/GLDC/Glycine complex." (PMID 39149564, 2024). "As shown in other cancer types, GLDC may sustain nucleotide synthesis during cell proliferation in HGSC tumorigenesis." (PMID 37923835, 2023). "However, additional work is needed to further test the biological importance of GLDC in ovarian and other cancers." (PMID 37923835, 2023). "GLDC is commonly up-regulated and plays important roles in many human cancers." (PMID 34244482, 2021). "In short, GLDC is involved in the occurrence and development of several cancers and may be a potential biomarker." (PMID 34790227, 2021). "Overexpression of GLDC promotes cellular transformation and induces dramatic changes in glycolysis and serine/glycine metabolism, leading to changes in pyrimidine metabolism and cancer cell proliferation." (PMID 28177894, 2017). "In addition, a recent study reported that glycine decarboxylase (GLDC), which is associated with Gly metabolism, was highly expressed in HER2-positive cancers." (PMID 28969000, 2017). "Although the abnormal expression of GLDC has been shown to promote tumorigenesis, it is unknown whether and how GLDC is regulated by posttranslational modifications and how its posttranslational modifications contribute to cancer progression." (PMID 34244482, 2021). "Thus, targeting of GLDC posttranslational modifications may provide a potential strategy for therapeutics of cancers." (PMID 34244482, 2021). "Enhanced expression of the GCS enzyme GLDC is detected in various cancers, although this reflects a requirement of cancer cells to remove glycine rather than a need for 1C units." (PMID 38698089, 2024). "According to the analysis of TCGA-ESCA data, we found that the expression of serine hydroxymethyltransferases 1, 2 (SHMT1, SHMT2) and glycine decarboxylase (GLDC), which catalyze the conversion of serine to glycine, were upregulated in ESCC cancer tissues compared with normal tissues." (PMID 36756157, 2023). "Although GLDC has been demonstrated to participate in regulating the development of tumors in some types of cancers, its roles in different cancers are controversial and not always consistent." (PMID 36275705, 2022). "Abnormal regulation of glycine decarboxylase is related to the occurrence of various human tumors, but roles of GLDC in different cancers are not always consistent." (PMID 36275705, 2022). "GLDC was expressed to a greater extent in the epithelial rather than in the stromal component of the luminal-B, HER-2, and TNBC types; however, the opposite pattern was observed in the luminal-A cancers." (PMID 24979213, 2014). "Although the precise mechanism of increased GLDC in HER2-positive cancers is unknown, a 20-fold increase in GLDC expression was seen in MCF10A cells after oncogenic transformation by KRASG12D, PIK3CAE545K, or MYCT58A, suggesting that HER2-positive cancer may be driven by certain HER2 oncogenes." (PMID 28969000, 2017).
cancer (continued). "Glycine decarboxylase (GLDC), an enzyme upregulated in several cancers, can drive the flux from serine to pyrimidine synthesis, but recent evidence indicates that serine, not glycine, supports cancer cell proliferation." (PMID 25250177, 2014).
metabolic disorder (5 papers, 2016 to 2024). "It has been found that glycine decarboxylase mutants can cause metabolic disorders in microalgae, glycine accumulation, and death, and in Streptomyces griseus, the deactivation of glycine lytic system will lead to sensitivity to glycine." (PMID 35615519, 2022). "How these observations integrate with the proposed role of GLDC in metabolic disease is a question that remains to be answered." (PMID 34342168, 2021).
neurological disease (3 papers, 2020 to 2026). "Nonetheless, our studies establish that while glycine is an age-dependent signifier of GLDC defect, treatment for normalization of single carbon metabolic deficiency (a second expected consequence of Gldc mutation), diminishes prenatal defects that underlie mutation-based, neurologic disease." (PMID 33524012, 2021).
infection (2 papers, 2019 to 2022). The state of being infected such as from the introduction of a foreign agent such as serum, vaccine, antigenic substance or organism. "GLDC inhibition in the H1N1‐infected BALB/c mice recapitulated the amplified antiviral response and suppressed viral growth, indicating that temporal GLDC inhibition could achieve a potent protection to the infected mice from the fatal infection." (PMID 30498026, 2019). "Notably, AOAA provided an equivalent protection as zanamivir, a standard antiviral against influenza viruses, indicating that temporal GLDC inhibition could achieve a potent protection from fatal infection." (PMID 30498026, 2019). "Thus, GLDC inhibition in the H1N1‐infected mice significantly boosted the antiviral response, decreased the viral growth, and protected the mice from lethal infection." (PMID 30498026, 2019).
brain disease (1 paper, 2026). "Together these data reveal a novel GLDC mechanism that regulates catabolic mitochondrial energy processes in both attenuated and severe brain disease and suggest new targets in energy metabolism to treat nonketotic hyperglycinemia." (PMID 42055339, 2026).
GLDC also shares sentences with these, for which no sentence is quoted: gout (2 papers); leukemia (2); lung adenocarcinoma (2); microcephaly (2); thyroid cancer (2); acute myeloid leukemia (1); behavioral disorders (1); biotinidase deficiency (1); bipolar disorder (1); cardiofaciocutaneous syndrome (1); chronic myeloid leukemia (1); colon cancer (1); COVID-19 (1); craniorachischisis (1); dyslipidemia (1); germ cell tumor (1); glycine encephalopathy 1 (1); Hydrocephalus (1); Hyperglycinuria (1); Kabuki syndrome 1 (1); Krabbe disease (1); lymphoma (1); male infertility (1); Mowat-Wilson syndrome (1); myotubular myopathy (1); Niemann-Pick disease (1); prostate adenocarcinoma (1); psoriasis (1); pyridoxine-dependent epilepsy (1); sarcoma (1).
A further 9 diseases each share a sentence with GLDC in 1 paper.